THSD8 (thrombospondin type 1 domain containing 8)
Gene: Protein-coding gene on chromosome 19 (12,802,031 to 12,813,581, forward strand). Ensembl gene ENSG00000284491.
Homologues: Orthologues: chimpanzee THSD8 (97% identical), mouse Gm49661 (62% identical).